RFWD3 (ring finger and WD repeat domain 3)
Diseases named in the same sentence as RFWD3 in open-access papers (continued):
Sharing a sentence is not in itself a finding about the gene and the disease.
cancer (13 papers, 2019 to 2025). A tumor composed of atypical neoplastic, often pleomorphic cells that invade other tissues. "More intriguingly, a genome-wide association study revealed that RFWD3 was a susceptible site for malignant neoplasms, such as multiple myeloma and testicular germ cell tumor." (PMID 34712656, 2021). "Many disease‐associated mutations exist within the WDR domain, presenting RFWD3 as a potential anti‐cancer target." (PMID 31442339, 2019). "Interestingly, the reduced expression of RFWD3 has been associated with a better prognosis in certain cancer contexts." (PMID 40002911, 2025). "Therefore, the effect of RFWD3 deficiency on cancer relevant phenotypes was assessed using the RFWD3Δ/Δ cell lines." (PMID 38711848, 2024). "CircRFWD3 is derived from the RFWD3 gene, which has a susceptible site for malignant neoplasms." (PMID 35690612, 2022). "Such context-specific roles warrant further investigation to fully understand RFWD3’s contribution to cancer biology." (PMID 40002911, 2025). "The protein expression was increased in cancer cells and decreased in normal cells, indicating that the VPA-mediated bidirectional effect was associated with RFWD3." (PMID 33842359, 2021). "Our findings uncovered the molecular mechanism of the bidirectional effect of VPA under IR treatment both in vitro and in vivo, VPA would be able to target RFWD3 and trigger Rad51 ubiquitination for cancer radiotherapy." (PMID 33842359, 2021). "An increasing body of evidence has revealed the critical roles of RFWD3 in replication protein A (RPA)-mediated DNA damage in cancer cells." (PMID 34712656, 2021). "For example, while RFWD3’s role in DNA repair generally supports genomic stability, in certain cancers, its activity might contribute to the survival of damaged cells, facilitating tumor progression." (PMID 40002911, 2025). "Recently, studies have demonstrated the emerging roles of RFWD3 in cancers." (PMID 41117130, 2025). "In the context of cancer cells in particular, which undergo rapid proliferation and are often subject to genotoxic stresses such as chemotherapy, the role of RFWD3 in the FA and HR pathways of DNA repair is also crucial for the maintenance of genomic stability." (PMID 38711848, 2024). "RFWD3 plays a critical role in replication protein A (RPA)-mediated DNA damage in cancer cells." (PMID 34712656, 2021). "Since studies demonstrated that DDR proteins may be potentially targeted for cancer therapy, thus, it would be important to locate a drug that can specially target RFWD3-dependent Rad51 ubiquitination for cancer therapy." (PMID 33842359, 2021). "Therefore, VPA probably directly upregulates RFWD3 and then initiates Rad51 ubiquitination to disrupt the HR function so as to enhance IR effect for killing cancer cells." (PMID 33842359, 2021). "Thus, our findings uncovered the novel mechanism of bidirectional effect of VPA under IR treatment both in vitro and in vivo, VPA can directly target RFWD3 and then trigger Rad51 ubiquitination during cancer radiotherapy and limit radiotoxicity on normal cells." (PMID 33842359, 2021). "There exist a positive correlation between EZH2 and the five genes (CHEK1, MAD2L1, RFWD3, TRAIP, and TTK) in the majority of detailed cancer types as shown in the form of heatmap data." (PMID 34381492, 2021). "RFWD3 has been previously reported to participate in non-canonical signalling pathways distinct from its role in ICL repair in other cancer types." (PMID 38711848, 2024). "Moreover, we observed a positive correlation between RFWD3 level and Ki-67 expression in ENCORI Pan-Cancer Analysis Platform." (PMID 34712656, 2021). "Indeed, both RFWD3 and RAD18 are aberrantly overexpressed in a broad spectrum of cancers." (PMID 37728310, 2023). "Studies of RFWD3 in HGSOC have not been reported in the literature, and investigation in other cancer types has been limited." (PMID 38711848, 2024).
tumor (9 papers, 2016 to 2025). "Sting knockdown reduced CD8+ T cells, granzyme B+, IFN‐γ+, and NK cells, and increased MDSCs in tumor tissues, and reversed the immunophenotype caused by Rfwd3 knockdown, suggesting the role of STING inhibition in RFWD3‐caused pro‐tumor TME." (PMID 41117130, 2025). "Upregulation of RFWD3 promoted tumor growth and induced an immunosuppressive tumor microenvironment, while RFWD3 knockdown caused the accumulation of cytoplasmic dsDNA, which triggered the activation of STING‐IFN signaling to exert anti‐tumor immunity." (PMID 41117130, 2025). "This suggests that low RFWD3 expression can influence tumour genotype in a similar way to mutation of FA genes including BRCA1 and BRCA2." (PMID 38711848, 2024). "We have demonstrated that low expression of RFWD3 also leads to increased frequency of mutations in HGSOC tumours." (PMID 38711848, 2024). "In tumours, low RFWD3 expression was associated with increased tumour mutational burden, and complete response to platinum chemotherapy." (PMID 38711848, 2024). "In the TCGA-OV dataset, cases with low RFWD3 expression were associated with increased tumour mutational burden and mutation count." (PMID 38711848, 2024). "Rfwd3 knockdown caused an increase in the number of tumor‐infiltrating CD4+ and CD8+ T cells." (PMID 41117130, 2025). "Both the cases with low RFWD3 expression and those with mutations in other FA genes were found to have significantly higher non-synonymous tumour mutational burden (control VS RFWD3 low expression p=0.025; control VS FA mutated p<0.0001) compared with the control group." (PMID 38711848, 2024). "The subset of low RFWD3 expressing cases were further investigated to determine whether they were associated with differences in clinical outcomes and tumour phenotype." (PMID 38711848, 2024). "We found a significant increase in CD45+ immune cells in Rfwd3‐knockdown tumor samples compared with those in Rfwd3‐wild‐type tumors." (PMID 41117130, 2025). "We found that Rfwd3 overexpression significantly promoted tumor growth, while Trex1 knockdown significantly inhibited tumor growth, compared to control cell‐triggered tumors in the mice." (PMID 41117130, 2025). "Consistent with previous results, Rfwd3 knockdown significantly inhibited tumor growth compared to the control group mice." (PMID 41117130, 2025). "Tumor‐infiltrating immune cells were dissociated from tumors and analyzed by flow cytometry, and we found that overexpression of Rfwd3 significantly inhibited infiltration of CD4+ T cells, CD8+ T cells, NK cells, and DCs, and increased MDSCs." (PMID 41117130, 2025). "RFWD3, a potential tumor suppressor, functions as an ubiquitin E3 ligase and plays a key role in DNA replication, DNA damage repair, and the effective termination of these processes." (PMID 40002911, 2025). "We observed that Rfwd3 knockdown in tumors increased the number of tumor‐infiltrating natural killer (NK) cells and dendritic cells (DC) but decreased the number of myeloid‐derived suppressor cells (MDSC)." (PMID 41117130, 2025). "RFWD3 expression and association with clinical features was assessed using in silico analysis in the TCGA HGSOC dataset, and in a further cohort of HGSOC tumours stained for RFWD3 using immunohistochemistry." (PMID 38711848, 2024). "RFWD3 expression varies in HGSOCs, which can lead to functional effects at both the cellular and tumour levels." (PMID 38711848, 2024). "RFWD3 has been shown to mediate a wide range of tumour relevant functions, including genomic stability, response to ICL inducing chemotherapies, regulation of the cell cycle, proliferation and migration." (PMID 38711848, 2024). "This further demonstrates the value of using ICL inducing therapies over other options in the treatment of tumours with low RFWD3 expression." (PMID 38711848, 2024). "The role of RFWD3 in platinum resistance was further demonstrated in an analysis of HGSOC patient tumour samples." (PMID 38711848, 2024).
tumor (continued). "We build on this by providing evidence of a more definitive link between decreased RFWD3 expression and the acquisition of a genomic instability phenotype in tumours." (PMID 38711848, 2024). "In consistent with the result of in vivo imaging, the observations that tumor from mice injected RFWD3-silenced RKO cells displayed decreased volume and weight suggested a possible contribution of RFWD3 depletion in impairing tumorigenesis in these mice." (PMID 34712656, 2021). "We noticed that, from the immunohistochemistry analysis, RFWD3 expression was upregulated in 48 cases of tumor tissues, but only in 4 cases of normal tissues." (PMID 34712656, 2021). "On the contrary, RFWD3 overexpression promoted tumor growth and increased tumor weight, inhibited the tumor‐infiltrating CD8+ T cells, Granzyme B‐ and IFN‐γ‐expressing CD8+ T cells, and decreased the number of tumor‐infiltrating NK cells and DCs, but increased the proportion of MDSCs." (PMID 41117130, 2025). "However, Rfwd3‐promoted tumor growth was markedly inhibited by Trex1 knockdown, suggesting that RFWD3‐induced tumor progression was at least partially mediated by TREX1." (PMID 41117130, 2025). "We found that the expression levels of p‐STING, p‐TBK1, p‐IRF3, and p‐STAT1 were markedly increased in the Rfwd3 knockdown group compared to the shNC group, indicating that knocking down Rfwd3 in tumor cells results in activation of the STING pathway in adjacent immune cells." (PMID 41117130, 2025). "Further relevance analysis between genes and immunization revealed a decreased proportion of memory CD4+ T cells in the tumor group, with RFWD3 positively correlating with M1 macrophages, ZNF626 positively correlating with M2 macrophages, and SLK negatively correlating with M1 macrophages." (PMID 40002911, 2025). "Overexpression of RFWD3 promotes tumor growth with increased myeloid‐derived suppressor cells (MDSCs), while inhibition of RFWD3 increases intracellular dsDNA levels, activates the STING‐IFN signaling, decreases MDSCs, and enhances the efficacy of PD‐L1 blockade in murine NSCLC models." (PMID 41117130, 2025). "RFWD3 inhibition enhanced the anti‐tumor efficacy of ICI in vivo." (PMID 41117130, 2025). "However, Rfwd3‐triggered decrease in CD4+ T cells, CD8+ T cells, NK cells, and DCs, and increase in MDSCs were suppressed by Trex1 knockdown, suggesting that RFWD3‐induced pro‐tumor immune suppression depends on TREX1." (PMID 41117130, 2025). "Conversely, RFWD3 exhibited a decreased expression in tumor patients." (PMID 40002911, 2025). "This supports a role for RFWD3 expression in tumour platinum response." (PMID 38711848, 2024). "In future, RFWD3 may have utility as a biomarker of platinum sensitivity, or as a drug target for sensitizing tumours to platinum." (PMID 38711848, 2024). "As the siRNA data showed that changes in RFWD3 expression can modify response to platinum, the response of RFWD3Δ/Δ cells to a range of chemotherapeutic drugs was assessed, in order to identify potential strategies to best treat tumours with differing expression of RFWD3." (PMID 38711848, 2024). "However, low mRNA expression, defined as a Z-score of <-2 compared to tumours in the dataset with diploid RFWD3, occurred in 9% of cases (28/489)." (PMID 38711848, 2024). "Therefore, ICL inducing agents appear to be the most effective treatment for tumour cells with low expression of RFWD3." (PMID 38711848, 2024). "Conversely, high expression of RFWD3 may lead to a tumour with greater genomic stability, which may therefore accumulate fewer mutations, resulting in a lower degree of intratumour heterogeneity." (PMID 38711848, 2024). "Therefore, RFWD3 serves a different function in normal cells and tumor cells, and VPA can initiate the key switch of RFWD3-related ubiquitination to have a radio-bidirectional effect." (PMID 33842359, 2021).
tumor (continued). "In conclusion, our study highlighted RFWD3 may function as a tumor promotor in CRC via E2F1 transcriptional regulation of BIRC5, which might be used as a future therapeutic target for the more effective treatment of CRC." (PMID 34712656, 2021). "In the present study, we found that the mechanism of VPA in normal cells was opposite to tumor cells, RFWD3-dependent Rad51 ubiquitination was down-regulated, which means that VPA-mediated radioprotection was associated with preserving Rad51 activity and avoiding its ubiquitination by RFWD3." (PMID 33842359, 2021). "This may be reflective of the conflicting roles which RFWD3 plays in the tumour setting." (PMID 38711848, 2024). "After the administration of both VPA and IR, tumor growth was significantly inhibited comparing to IR alone (P < 0.01), the DSBs detected by γH2AX was enhanced, the protein level of Rad51 was inhibited, but RFWD3 protein level was increased as compared with IR treatment alone." (PMID 33842359, 2021). "We observed that Rfwd3 knockdown led to enhanced infiltration of CD8+ T cells in the tumor, with a tendency for infiltration toward the interior of the tumor tissue." (PMID 41117130, 2025). "Knockdown of RFWD3 inhibited proliferation and increased secretion of IFN‐β at the cellular level, and repressed tumor growth with an increase in CD4+, CD8+, Granzyme B+/CD8+, IFN‐γ/CD8+, NK, and DC cells and a decrease in MDSCs." (PMID 41117130, 2025). "We found that RFWD3 and TREX1 were highly expressed in tumor tissues when compared with the counterpart adjacent normal lung tissues." (PMID 41117130, 2025). "We studied the effects of Rfwd3 knockdown in tumor cells on the STING pathway in adjacent tumor‐infiltrating immune cells, by flow cytometric sorting of CD45+ cells from tumor tissues and western blot analysis of lysates of these CD45+ cells." (PMID 41117130, 2025). "RFWD3 inhibited cGAS‐STING signaling by stabilizing TREX1 and degrading dsDNA, leading to the accumulation of MDSCs and suppression of anti‐tumor immunity." (PMID 41117130, 2025). "The results showed that RFWD3 knockout significantly increased PHGDH expression, reduced the NAD+/NADH ratio, and elevated serine levels of the subcutaneous tumor." (PMID 40019400, 2025). "Our findings uncovered RFWD3-dependent Rad51 ubiquitination was the novel mechanism of VPA-mediated radio-bidirectional effect, VPA is a potential adjuvant treatment for tumor RT." (PMID 33842359, 2021). "Consistently, knockdown of Rfwd3 did not affect tumor growth or Ki67+ cell proportion in Rag1 KO mice." (PMID 41117130, 2025). "To test this hypothesis, we investigated the combined effects of RFWD3 inhibition (by shRfwd3 transfection) and an anti‐PD‐L1 antibody (α‐PD‐L1) in LLC tumor‐bearing mice." (PMID 41117130, 2025). "Results showed that the tumor growth inhibition effect induced by Rfwd3 knockdown combined with PD‐L1 was reversed after blocking the STING pathway, indicating that the synergistic effect between RFWD3 inhibition and PD‐L1 blockade depends on STING pathways." (PMID 41117130, 2025). "Interestingly, the anti‐tumor effect of silencing Rfwd3 was markedly inhibited by Sting knockdown, suggesting that the STING pathway has an important role in RFWD3‐induced tumorigenesis." (PMID 41117130, 2025). "Estrogen promotes cell proliferation and inhibits apoptosis by upregulating ZNF626 and SLK genes and downregulating the RFWD3 gene, while also leading to a decline in memory CD4+ T cells and a shift in macrophage phenotypes from M1 to M2 within the tumor inflammatory microenvironment." (PMID 40002911, 2025). "Inhibition of RFWD3 activates the IFN pathway to enhance the innate immune response, suggesting that targeting RFWD3 could convert immunosuppressive “cold” tumors into immunoreactive “hot” tumors to improve the tumor response to ICI therapy." (PMID 41117130, 2025). "We found that knockdown of Rfwd3 did not significantly inhibit tumor growth in NSG models." (PMID 41117130, 2025).
tumor (continued). "To determine whether the effects of RFWD3 on tumor growth are immune‐dependent or not, we subcutaneously inoculated shNC‐ or shRfwd3‐transfected LLC cells into NOD/ShiLtJGpt‐Prkdcem26Cd52Il2rgem26Cd22/Gpt (NSG) mice or Recombination‐Activating Gene 1 (Rag1) KO mice." (PMID 41117130, 2025).
infection (1 paper, 2021). The state of being infected such as from the introduction of a foreign agent such as serum, vaccine, antigenic substance or organism. "The infection/knockdown efficiency of shRFWD3-1 in RKO and HCT 116 cells was evaluated by observing fluorescence inside cells, qRT-PCR and western blot analysis, which validated downregulation of RFWD3 in the presence of shRFWD3-1." (PMID 34712656, 2021).
RFWD3 also shares sentences with these, for which no sentence is quoted: genetic disease (2 papers); glioma (2); autosomal recessive disease (1); bone marrow failure (1); brain tumors (1); large cell lung cancer (1); melanoma (1); photosensitive disorders (1); serous ovarian cancer (1).